IL4 (interleukin 4)
Diseases named in the same sentence as IL4 in open-access papers (continued):
Sharing a sentence is not in itself a finding about the gene and the disease.
lymphoma (continued). "The role of IL4 in tumor initiation and progression is not fully understood, however, it was shown that IL4 can promote tumor growth in preclinical models of murine lymphoma." (PMID 31779626, 2019). "Interleukin-4 (IL-4) is closely associated with the CD4+ T helper cells and EL4 T lymphoma cells (Mus musculus)." (PMID 31052435, 2019). "We initiated our studies using CH12F3-2 cells, a unique mouse lymphoma system that undergoes class-switching from IgM to IgA in the presence of αCD40, IL-4, and TGFβ (CIT)." (PMID 30619193, 2018). "Our investigations into the IL-4/IL-13 axis indicated that global expression of IL-4Rα was required for optimal pro-tumor effects of apoptotic lymphoma cells, as well as optimal TAM accumulation." (PMID 25702581, 2015). "Among the 11 analyzed cytokines, IL-8, IL-4, and IL-1β levels were significantly different from control depending on the lymphoma subtype using one-way analysis of variance among control and lymphoma subtypes (P = 6.69E−05, 7.46E−05, and 0.0043, respectively)." (PMID 26674732, 2015). "Fifteen of the 31 lymphoma patients (48%) exhibited increased IL-10 and 5 patients (16%) exhibited increased IL-4 levels." (PMID 25541655, 2014). "Another explanation for the MC-promoting effect of NPM-ALK would be that malignant cells in the NPM-ALK-induced lymphomas produced cytokines that induced MC growth, such as IL-3 or IL-4." (PMID 21297223, 2010). "The IL4 and BCR-induced mTOR activation was reduced by CREBBP mutants and augmented by mutant STAT6, establishing a link between STAT6 mutations and mTOR regulated pro-growth pathways in lymphoma." (PMID 39910284, 2025). "We could indeed confirm direct interaction of PARP14 and STAT6 in IL-4 stimulated lymphoma cells by IP of 3xFlag-tagged STAT6 and immunoblotting for PARP14." (PMID 35851155, 2022). "Moreover, increased IL-4 concentration is observed frequently in advanced stages of CTCL; it correlates with T-cell immunophenotype differences found in advanced lymphoma stages and is associated with clonality of MF and SS cells." (PMID 34948183, 2021). "In summary, EBV transformation can induce B-cell susceptibility to HIV-1 infection in vitro in a CD4- and CXCR4-dependent manner, similar to IL-4 and/or CD40L stimulation of B cells and CD4 can be detected on peripheral blood B cells and lymphoma cells in EBV-associated diseases." (PMID 32576602, 2020). "THRLBCL is associated with a prominent component of reactive T cells, which may be related to interleukin-4 production by the lymphoma cells." (PMID 26904321, 2016). "As such, PARP14 has been implicated in mediating IL-4 induced attenuation of caspase-3 activation, i.e., increased PARP14 levels could contribute to protection against apoptosis and provide a survival advantage to STAT6MUT lymphoma cells." (PMID 35851155, 2022). "STAT6 mutations, frequently detected in follicular lymphoma and other BCLs, point to a potential overlap in the IL-4/JAK/STAT6 signaling pathway involved in both AD and lymphoma pathogenesis." (PMID 40297814, 2025). "Lymphoma cells enhanced the expression of p-PERK, p-IRE1α, ATF6, IL-6, IL-4, p-AKT, CD9, CD63 and PD-L1 in bone marrow-derived macrophages by mediating the Notch-1 signaling pathway." (PMID 38261741, 2024). "When IXA4 was used, the expressions of IL-4 and IL-6 were upregulated in WT + lymphoma cell + IXA4 group compared with WT + lymphoma cell group." (PMID 38261741, 2024). "The effect of different cycles of R-CHOP on IL-4, BDNF and neopterin levels of all lymphoma patients (n = 70)." (PMID 39355088, 2024). "Both compounds inhibited the IL-4 pathway by acting on IL-4Rα, JAK3, and STAT6 activation in lymphoma cells (DND39) and fibroblasts (NIH3T3)." (PMID 36364420, 2022). "However, in various types of lymphomas, IL-4 may behave differently." (PMID 33321722, 2020).
lymphoma (continued). "The IL-4/7 CCR rendered EBVSTs resistant to IL-4 signaling, and greatly enhanced tumor control in an EBV lymphoma xenograft mouse model, where T cells can be activated in a locally restricted manner in the TME." (PMID 32570906, 2020). "IL-4 levels are raised in sera of patients; however, it does not always concern the cases of low-grade lymphoma." (PMID 34948183, 2021). "This resistance mechanism provides a strong rationale for combining IL-4 pathway inhibitors with immune checkpoint blockades, with the goal of restoring anti-tumor immunity and improving treatment outcomes, particularly in CD30-positive lymphomas such as mycosis fungoides." (PMID 40864740, 2025). "BCAT1 inhibition blunted BCR/TLR9, but not CD40L/IL4-triggered B-cell proliferation, IL10 expression and BCR/TLR pathway-driven lymphoma xenograft outgrowth." (PMID 38854072, 2024). "Expression of phosphorylated STAT6 without IL4/IL13 transcription has been demonstrated in PMBL, suggesting that STAT6 activation in these lymphomas is not due to an autocrine IL4/IL13 secretion." (PMID 37835560, 2023).
eczema (40 papers, 2012 to 2025). "Conversely, in eczema, conventional DCs (cDCs) are known to induce a Th2-cell-associated immune response, resulting in T-cell secretion of IL-4, IL-5, IL-9, and IL-13." (PMID 41009640, 2025). "AD is also an immune system skin disorder, and the secretion of cytokines, especially IL-4, IL-12, and IL-13, causes barrier defects and inflammation, resulting in the clinical features of eczema." (PMID 37569742, 2023). "For refractory eczema, emerging biologic therapies such as the IL-4/IL-13 receptor antagonist dupilumab have shown promising results in some patients with STAT3-HIES." (PMID 41458089, 2025). "Conversely, the clinical appearance of eczema is more uniform and characterised by a strong Th2 component involving IL-4 and IL-13 over-production." (PMID 41009640, 2025). "Experimental studies demonstrate its capacity to suppress nuclear factor‐κB‐mediated inflammatory pathways, reducing key cytokines such as IL‐4 and IL‐13, which drive eczema pathogenesis." (PMID 41292677, 2025). "This is a negative regulator of pro-inflammatory cytokines, which causes a decrease in the inflammatory mediator’s response, such as IL-4 and IL-13, to prevent eczema." (PMID 41011120, 2025). "Dupilumab, an anti-IL-4Rα antibody that blocks IL-4 and IL-13 signaling, was approved for treatment of moderate to severe eczema (AD) in the United States in 201725." (PMID 40312358, 2025). "In our model, our objective was to emulate the acute irritation response by employing DNCB and IL4 to achieve a higher semblance of eczema." (PMID 38139083, 2023). "CD4+ T cells show Th2 skewing and production of IL-4, IL-5, IL-13, contributing to the atopic phenotype seen in these patients of eczema and eosinophilia." (PMID 37727514, 2023). "Monoclonal antibodies targeting allergic immune effectors, including omalizumab (IgE), dupilumab (IL-4 and IL-13), reslizumab, benralizumab, and mepolizumab (IL-5), have shown efficacy in treating the eczema and other allergic manifestations." (PMID 37727514, 2023). "CTGO significantly improved the skin surface and histopathological characteristics of eczema-affected rats, downregulated the expression of IL-4, TLR4, NF-κB (p65), IL-1β, and TNF-α, and upregulated the expression level of IFN-γ." (PMID 35907999, 2022). "The expression levels of IFN-γ and IL-4 in normal subjects maintained a relatively balanced state, which is lost in patients with eczema." (PMID 35907999, 2022). "Typical therapy for both eczema and EoE includes medications, such as steroids and dupilumab (a monoclonal antibody against IL4 and IL13), known to also be effective in Th2-driven atopic inflammation." (PMID 36118171, 2022). "Biochemical indexes are indirectly related indexes, and IL-4 and other biochemical indexes will increase after the animal eczema model has been successfully established." (PMID 35907999, 2022). "The pathogenesis in eczema is complex, and many different cytokines are involved, such as IL-4, IL-5, IL-13, and IL-17." (PMID 33815560, 2021). "In summary, the data presented in this study suggest that the four‐way gene model involving IL13 rs20541, IL4 rs2243250, ADRB2 rs1042713, and FCER1B rs569108 was significantly associated with the development of eczema in Chinese Han toddlers." (PMID 33277970, 2021). "The four‐gene model involving IL13 rs20541, IL4 rs2243250, ADRB2 rs1042713, and FCER1B rs569108 was significantly associated with the development of eczema in Chinese Han toddlers." (PMID 33277970, 2021). "This accounts for many atopic features present in eczema patients, including elevated IL-4, 5 and 6 productions by T cell, increased IgE synthesis, reduced IFN-γ production and impaired cell-mediated immune response." (PMID 22682479, 2012).
eczema (continued). "(c) The immunological system of eczema focused on T helper type 2 (Th2) cell-derived cytokines, including interleukin (IL)-4 and IL-13, and keratinocyte-derived cytokines, as well as thymic stromal lymphopoietin (TSLP) and IL-33, which contribute to Th2-mediated skin inflammation in AD." (PMID 41011120, 2025). "Clinical studies suggest that the mechanism of MTMZM in treating eczema may be related to regulating the expression of IL-2, IL-4, IL-10, and γ-IFN; therefore, it can improve the body's immunity and reduce inflammatory response." (PMID 40933470, 2025). "It is interesting that IFN‐γ increases and IL‐4 decreases melanogenesis, implying that type 1 eczema and type 2 eczema might have opposite effects on hyperpigmentation." (PMID 39301836, 2025). "However, following the initiation of dupilumab therapy—a dual IL-4 and IL-13 receptor antagonist—the patient experienced a substantial reduction in his Eczema Area and Severity Index score." (PMID 39046661, 2024). "Under the action of allergens in the skin system, numerous inflammation-mediated factors, such as TNF-α, IL1β, and IL-4, are secreted during epidermal keratinization, all of which interact with each other in the pathogenesis of eczema, thus influencing the development and prognosis of the disease." (PMID 35907999, 2022). "Consistent with the finding that eczema is manifested by both contact dermatitis and AD, IFN‐γ, and IL‐4/IL‐13 increase the production of hyaluronic acid and decrease the expression of E‐cadherin." (PMID 39301836, 2025). "In eczema, TNF-α, IL-1β, and IL-4 expression increases, binding to receptors activates NF-κB, stimulating inflammatory mediator production (e.g., TNF-α, IL-1β, and IL-4), creating a positive feedback loop." (PMID 40933470, 2025). "IL4, IL13, IL1RL1, IL18R1 and TSLP are also the only proteins found to be common to eczema and rhinitis." (PMID 28598986, 2017). "Huangbo has also become a staple for eczema treatment, as it could decrease mRNA expressions of proinflammatory cytokines (like IL-1β, TNF-α, IL-17, IL-4, and IL-13)." (PMID 41311842, 2025). "The experimental results showed that CTGO could significantly reduce IL-4 levels and increase IFN-γ levels, suggesting that CTGO may play a role in the treatment of eczema by promoting Th1/Th2 homeostasis by down-regulating IL-4 levels and up-regulating IFN-γ levels." (PMID 35907999, 2022). "In terms of efficacy, data from clinically used drugs strongly suggest that targeting IL-13 only, as opposed to IL-13 and IL-4, may be effective in eczema while being more selective." (PMID 30759882, 2019). "In addition, IL-4 and IFN-γ mirror the Th1/Th2 imbalance and the state of inflammation of eczema." (PMID 28874171, 2017). "Thus, fast improvement of the erythrodermic ichthyosis and eczema lesions using a combination of Dupilumab/Guselkumab indicate clinical evidence and proof‐of‐principle for an effective, safe, well‐tolerated treatment of CIE using anti‐IL‐23 and anti‐IL‐4 therapy in combination, if needed." (PMID 35665208, 2022).
endometriosis (40 papers, 2013 to 2025). The growth of functional endometrial tissue in anatomic sites outside the uterine body. "Accordingly, we aim to investigate the role of serum miR-17, IL-4, and IL-6 as early diagnostic markers of endometriosis." (PMID 29901577, 2018). "The purpose of this study was to investigate the role of serum miR-17, IL-4, and IL-6 as early diagnostic markers of endometriosis." (PMID 29901577, 2018). "In short, the present study characterizes the role of miR-17, IL-4, and IL-6 in the pathogenesis of endometriosis, suggesting the feasibility of using miR-17 and selected cytokines as a noninvasive diagnostic test for the detection of endometriosis." (PMID 29901577, 2018). "On the basis of the presence and activity of selected cytokines typical for various types of cellular response, it was indicated that the development of endometriosis is favored by Th2 cellular response and the associated cytokines, IL-4, IL-5, IL-6, IL-10 among others." (PMID 24298555, 2013). "SOCS1 dysregulation may exacerbate the IL-4 and IL-13 properties associated with endometriosis." (PMID 36120440, 2022). "Vaccines using Bacillus Calmette–Guérin (BCG) are among the most effective immunotherapeutic agents that stimulate NK cells and prevent the typical IL6, IL10, and IL4 responses observed in endometriosis." (PMID 38543097, 2024). "In endometriosis implants, IL-4 encourages eotaxin secretion, leading to angiogenesis and the progression of lesions." (PMID 39767772, 2024). "CCL11, also known as eotaxin-1, is an inflammatory biomarker that was reportedly elevated in peritoneal fluid and eutopic and ectopic endometrium of women with endometriosis, and induced in endometriotic stromal cells by interleukin-4 (IL-4)." (PMID 38999962, 2024). "The TGF-β1 and PDGF-BB produced by Tregs promote lesional growth, EMT, FMT, and fibrosis in endometriosis, while the IL-33 secreted by endometriotic cells transform Tregs into Th2-like Tregs, producing more profibrotic cytokines IL-13, IL-4, and even TGF-β1." (PMID 36428461, 2022). "IL-1β, IL-6, and IL-15 expressions were lower, and IL-4 was higher in endometriosis lesions compared to that in eutopic endometrium in the proliferative phase." (PMID 35269619, 2022). "They showed that the number of NKT cells, as well as IFN-γ, and IL-4 levels, were inversely correlated with endometriosis stage, supporting the correlation between the number of NKT cells and the severity of endometriosis." (PMID 35576870, 2022). "In the secretory phase, IL-2 and IL-4 expression decreased by 64.3% and 82.1%, respectively, in the non-endometriosis endometrium, compared to the eutopic endometrium." (PMID 35269619, 2022). "There is also an increase in the proinflammatory and anti-inflammatory cytokines IL-1, IL-4, IL-6, IL-8, IL-10 and TNFα in the serum and in peritoneal fluid of women with endometriosis, particularly in advanced stages." (PMID 35888644, 2022). "Shifts towards the Th2 immune response have been found to be involved in endometriosis, with a relative predominance of IL-4 and IL-10." (PMID 34289871, 2021). "Overall, our data demonstrated that rhIL-37 markedly inhibited the development of endometriosis via increasing the ratio of Th1/Th2 cells by inhibiting the production of IL-4 in DCs and promoting the maturation of DCs." (PMID 34429116, 2021). "In particular, M2a macrophages, which can be induced by IL-4 or IL-13—two typical Th2 cytokines—have been reported to be critically involved in fibrogenesis of endometriosis." (PMID 33381124, 2020). "The continuous activation of MCs and the production of IL-4 and IL-6 are related to the production and maintenance of persistent inflammation, leading to deterioration of endometriosis." (PMID 32145751, 2020). "The results showed miR-22 expression decreased along with the higher endometriosis grade significantly whereas the level of IL-4 and IL-6 markedly decreased." (PMID 29901577, 2018).
endometriosis (continued). "In order to explore the role of miR-17, IL-4, and IL-6 in the development of endometriosis, the expression of these indexes was analyzed using qPCR." (PMID 29901577, 2018). "The present study characterizes the role of miR-17, IL-4, and IL-6 in the pathogenesis of endometriosis, suggesting the feasibility of using miR-17 and selected cytokines as a noninvasive diagnostic test for the detection of endometriosis." (PMID 29901577, 2018). "And the level of miR-17, IL-4, and IL-6 was analyzed based on different grades in endometriosis group." (PMID 29901577, 2018). "Interleukin-4 is released locally and stimulates proliferation of endometriotic tissue, contributing to the formation of adhesions in the course of endometriosis." (PMID 24298555, 2013). "One study showed significantly higher levels of IL-4 in serum and peritoneal fluid in adolescents with endometriosis, which may be used in future work on the development of a biomarker of this disease." (PMID 37446108, 2023). "Moreover, IL-4 promotes the proliferation of endometriotic stromal cells (ESCs) and endometriosis progression by activating p38 mitogen-activated kinases (p38 MAPKs), stress-activated protein kinase/c-Jun kinase and p42/44 MAPK." (PMID 35935991, 2022). "The IL-4-mediated proliferative effect was canceled by the anti-IL-4 receptor treatment, suggesting that IL-4 may have a positive regulatory role in endometriosis development." (PMID 36362231, 2022). "Although the precise molecular processes of Th2 remain unknown, IL-4 in peritoneal fluid is elevated in endometriosis patients." (PMID 36362231, 2022). "IFN-γ, TNF-α, IL-4, and IL-13 are the important cytokines for Th1 and Th2 cells, hence, above results indicated that rhIL-37 maybe improve endometriosis through regulating Th1 and Th2 differentiation." (PMID 34429116, 2021). "Overall, rhIL-37 could protect against endometriosis through increasing the ratio of Th1/Th2 cells via inducing DCs maturation and inhibiting IL-4 expression in the DCs." (PMID 34429116, 2021). "It was reported that the concentration of Th1 cell-related cytokines like interferon-γ (IFN-γ) was lowly expressed, while Th2 cell-related cytokines like interleukins (IL)-4, IL-10, and IL-13 were highly expressed in the serum of the patients with endometriosis." (PMID 34429116, 2021). "The levels of IL-4 and IL-6 are increased remarkably in women with endometriosis." (PMID 32145751, 2020). "Moreover, the IL-4 and IL-6 expression exhibited an increase in endometriosis compared to that in control group (P < .05)." (PMID 29901577, 2018). "Confirmation of this phenomenon may be the decrease of the IL-4 after endometriosis excision combined with immunomodulation." (PMID 24298555, 2013). "Furthermore, recent studies have shown that serum IL-4 levels are notably elevated in patients with endometriosis compared to controls, suggesting that IL-4 could serve as a valuable biomarker for diagnosing the condition." (PMID 39767772, 2024). "Th2 cells, through the secretion of IL-4 and IL-13, which mediate the differentiation of resident fibroblasts and the recruitment of fibrocytes to myofibroblasts, may contribute to pelvic fibrosis in women with endometriosis." (PMID 37446108, 2023). "IL-4 and IL-13 type I and II receptor signaling pathways are linked to Signal Transducer and Activator of Transcription 6 (STAT6) expression, responsible for mediating IL-4 and IL-13 immune signaling, increase proliferation, adhesion and viability of endometriosis lesions." (PMID 36120440, 2022). "Therefore, endometriosis progression may be stimulated by an IL-4 dependent, local increase in estrogen concentration." (PMID 35935991, 2022). "Besides, the levels of serum IL-4 and IL-13 were upregulated in the mice with endometriosis, but rhIL-37 treatment could effectively decline the levels of them." (PMID 34429116, 2021).